OR1E2 (olfactory receptor family 1 subfamily E member 2)
Description:
Odorant receptor.
Synonyms: OR17-135; OR17-136; OR17-93; OR1E4; OR1E7; OST529
Tractability: Antibody: its Gene Ontology location is reachable by antibodies, with high confidence; UniProt places it where antibodies can reach, with medium confidence; UniProt predicts a signal peptide or a membrane-spanning region.
Gene: Protein-coding gene on chromosome 17 (3,432,870 to 3,433,841, reverse strand). Ensembl gene ENSG00000127780.
Subcellular location: Cell membrane
Pathways (Reactome):
Sensory Perception: Expression and translocation of olfactory receptors
Gene Ontology:
Molecular function: olfactory receptor activity; signaling receptor activity; G protein-coupled receptor activity
Biological process: sensory perception of chemical stimulus; signal transduction; detection of chemical stimulus involved in sensory perception of smell; G protein-coupled receptor signaling pathway
Cellular component: plasma membrane; membrane
Genetic constraint (gnomAD): Loss-of-function variants: 8 observed, 13.08 expected, observed/expected ratio (o/e) 0.61, 90% interval 0.36 to 1.1. The upper end of that interval is the gene's LOEUF score, 1.1, which puts it in group 4 of 6, group 1 being the genes least tolerant of losing a copy. Missense variants: 344 observed, 395.78 expected, observed/expected ratio (o/e) 0.87, 90% interval 0.8 to 0.95. Synonymous variants: 135 observed, 160.77 expected, observed/expected ratio (o/e) 0.84, 90% interval 0.73 to 0.97.
Homologues: Orthologues: chimpanzee OR1E2 (95% identical), macaque OR1E2 (90% identical). Paralogues in human: OR1E1 (92% identical), OR1J4 (59% identical), OR1J2 (58% identical), OR1J1 (56% identical), OR1F1 (54% identical), OR1N1 (54% identical), OR1N2 (53% identical), OR1G1 (53% identical), OR7C1 (52% identical), OR1M1 (52% identical), OR7C2 (52% identical), OR7D2 (52% identical), and 116 more.
Diseases named in the same sentence as OR1E2 in open-access papers:
OR1E2 is named in the same sentence as 1 disease in open-access papers, as found by Europe PMC text mining. Sharing a sentence is not in itself a finding about the gene and the disease.
OR1E2 shares sentences with these, for which no sentence is quoted: breast carcinoma (1 paper).